IL6R (interleukin 6 receptor)
Diseases named in the same sentence as IL6R in open-access papers (continued):
Sharing a sentence is not in itself a finding about the gene and the disease.
COVID-19 (continued). "IVW meta-analysis of MR estimates of IL6R blockade for UK Biobank and COVID-19 HGI outcomes." (PMID 36716318, 2023). "However, despite transforming the treatment options for COVID-19, IL-6R inhibition is still ineffective in a fraction of patients." (PMID 37215114, 2023). "In previous studies, IL-6R antagonists were mainly used for the treatment of autoimmune diseases, but recently, IL-6R-targeting inhibitors were also found to be effective in the treatment of severe and critical COVID-19." (PMID 35382755, 2022). "In the COVID-19 scenario with mAb concentrations at 1% of those in plasma, IL-6 bioactivity was minimally inhibited even with repeated daily injections of anti-IL-6 or anti-IL-6R mAb, either alone or in combination." (PMID 35928820, 2022). "In this case series of three patients with severe COVID-19, we focus on the rationale for utilization of tocilizumab, an anti-interleukin-6 receptor antibody, which could block the signal transduction pathway of interleukin-6." (PMID 36705224, 2022). "Despite the evolution in COVID-19 management over the course of the pandemic, including the use of steroids, Janus kinase inhibitors, interleukin-6 receptor inhibitors, antiviral agents, and anticoagulation treatments, the RAM that we developed shows acceptable discrimination and good calibration." (PMID 35887713, 2022). "The limited use of interleukin-6 receptor antagonists/immune-modulating drugs, patient age, and other unexplored pathophysiological mechanisms determine the progression of vaso-occlusive crises in COVID-19 scenarios." (PMID 35494937, 2022). "One mechanism might be inflammation, with recent findings from Mendelian randomisation studies and two randomised controlled trials converging on IL6R inhibition as an effective therapeutic approach for COVID-19." (PMID 35031696, 2022). "Moreover, the anti-IL-6 receptor (IL-6R) antibody tocilizumab can improve the prognosis of critical COVID-19 patients, as it can bind to IL-6R and block downstream signal transduction." (PMID 36186987, 2022). "TCZ is a neutralizing antibody against IL-6 and IL-6R and blocks both classical and signal transduction pathways, and it is currently the most preferred IL-6 inhibitor in the treatment of patients with COVID-19/ARDS." (PMID 36115998, 2022). "Finally, a targeted Mendelian randomization analysis of the clinically widely examined interleukin-6 receptor (IL-6R) drug target has also provided supporting evidence for its therapeutic inhibition in the treatment of severe COVID-19." (PMID 35768520, 2022). "IL-6R blockade may represent an essential strategy for interrupting the inflammatory process in COVID-19; however, the success has been limited." (PMID 35631442, 2022). "The authors thus suggested that both miRNAs, along with enhanced lncRNA levels, may promote IL-6R/CCL2 translation in COVID-19 patients, contributing to IL-6-induced cytokine storms." (PMID 35207576, 2022). "Among these three, only ABO and IL-6R proteins had some evidence of genetic colocalisation with posterior probabilities (PP.H4) more than 0.9 and 0.4, respectively, of a shared genetic signal between protein and COVID-19 phenotype." (PMID 34402426, 2021). "Tocilizumab is an interleukin-6 receptor antagonist, which may counteract the inflammatory response in patients with severe COVID-19." (PMID 33920781, 2021). "Along with plant-produced mAbs against the S protein, plant-produced anti-IL-6R mAb and mAbs against that of other cytokines may provide a less-expensive, yet equally potent treatment option for COVID-19 and other inflammatory diseases." (PMID 34835296, 2021). "It was proposed that early intervention with interleukin-6 receptor blockade by Tocilizumab could effectively control the progression to hypoxemic respiratory failure or death of severe COVID-19 patients." (PMID 34659270, 2021).
COVID-19 (continued). "The currently recommended use of corticosteroids and interleukin-6 receptor antagonists (e.g. tocilizumab) for the treatment of COVID-19 may impact the frequency of bacterial infections in this population." (PMID 34717761, 2021). "Thus, as anti-IL-6R interventions are continuing to be assessed for COVID-19, there is a potential opportunity for plant-based production of these expensive mAb treatments to ease the economic burden of treating hospitalized patients." (PMID 34835296, 2021). "We have identified gene clusters associated with CRC, COVID-19, and biochanin A. Bioinformatic analysis further showed the involvement of six core targets of biochanin A in the treatment of CRC/COVID-19, including EGFR, CCND1, IL2, IL1A, IL6R, and PPARG." (PMID 34931923, 2021). "Thus, the use of IL-6R antagonists has been suggested as a potential therapy for severe COVID-19-related pneumonia cases." (PMID 34276355, 2021). "Moreover, the IL6R inhibitor tocilizumab was reported for COVID-19 treatment, and another IL6R inhibitor, sarilumab, is being evaluated in clinical trials (ClinicalTrials.gov Identifier: NCT04327388)." (PMID 33413329, 2021). "In conclusion, we reasonably postulate that strategies targeting IL-6R trans signaling may be beneficial for the prevention and treatment of patients with severe COVID-19 and pre-existing cardiac disease or new onset myocardial damage, even HF." (PMID 33404925, 2021). "However, the current World Health Organization guidelines on drugs for COVID-19 only strongly recommend two drugs (corticosteroids and interleukin-6 receptor blockers) as a treatment for patients with severe or critical COVID-19." (PMID 35011857, 2021). "Next to research into effective vaccines and potential antiviral drugs, numerous studies have focused on host-directed strategies as an adjunctive approach to improve the outcome of COVID-19 patients, especially anti-inflammatory therapies such as anti-IL-6R antibodies or recombinant IL-1Ra." (PMID 34195785, 2021). "Therefore, IL-6 and IL-6R are receiving more attention as potential therapeutic targets for the treatment of COVID-19." (PMID 33658032, 2021). "Therefore, immune checkpoint inhibitors combined with IL-6/IL-6R-specific antibodies are expected to be a new hope for COVID-19 patients." (PMID 33240265, 2020). "Various clinical trials are currently under way using immunomodulatory IL-1 and IL-6 inhibitors or anti-IL-6R antibodies (anakinra, tocilizumab, siltuximab, and sarilumab) in patients with COVID-19 (COVID-19 Treatment Guidelines Panel, 2020); limited data, however, is yet available." (PMID 33692684, 2020). "In the present study, we investigated the distribution of genetic variations in IL6 and IL6R genes, which may be employed as prognostic and pharmacogenetic biomarkers for COVID-19 and neurodegenerative diseases." (PMID 33339153, 2020). "Tocilizumab, an interleukin-6 receptor antibody, has been utilized for the treatment of cytokine storm in a number of severe inflammatory conditions, including in patients with severe coronavirus disease 2019 (COVID-19)." (PMID 33072589, 2020). "In clinical trials, the blocking of interleukin-1 receptor (IL-1R) with anakinra and blocking of Interleukin-6 receptor (IL-6R) with tocilizumab resulted in significant improvement in COVID-19 patients, which suggests that SARS-CoV-2-related damage is caused by cytokines." (PMID 32574248, 2020). "Tocilizumab, a monoclonal antibody targeting the interleukin-6 receptor (IL-6R), demonstrated clinical benefits in some COVID-19 patients by reducing the hyper-inflammatory responses; however, it was also observed that some patients were refractory to tocilizumab treatment." (PMID 33553219, 2020). "Importantly, we found significantly higher expression of secreted IL-6, as have others, especially in ICU patients, underscoring the rationale for testing anti-IL-6 or anti-IL-6R antibodies in severely ill COVID-19 patients." (PMID 32829467, 2020).
COVID-19 (continued). "Blocking the IL-6 signaling pathway with IL-6R antibody can inhibit CRS, thus the IL-6R antagonist Tocilizumab may be key to reducing the mortality of CRS of severe COVID-19." (PMID 32878118, 2020). "Furthermore, ERAPs modulate the proteolytic cleavage of IL-6 receptor (IL-6Rα) a function which can improve the clinical conditions in COVID-19 patients, as recently documented following its pharmacological inhibition by Tocilizumab." (PMID 32847031, 2020). "Current results from clinical studies evaluating IL-6R inhibitors in COVID-19 are inconsistent." (PMID 33584679, 2020). "Indeed, controlled clinical trials are underway around the world to test the treatment of IL-6 and IL-6R antagonists for COVID-19 patients with severe respiratory complications." (PMID 33178109, 2020). "Currently, TCZ is clinically trialed for targeting IL-6R in COVID-19 patients." (PMID 32636755, 2020). "Clinical trials are ongoing to assess the efficacy of reducing systemic inflammation using anti-inflammatory drugs for severe COVID-19 patients, including humanized monoclonal antibodies that bind and block the interleukin-6 receptor (IL-6R): Tocilizumab and Sarilumab." (PMID 32457811, 2020). "Having focused exclusively on corticosteroids, this analysis may overestimate the uptake of WHO recommendations for severe COVID-19 given the lesser availability and higher costs of other recommended therapies, such as interleukin 6 receptor blockers and baricitinib." (PMID 38147336, 2023). "Hence, the evaluation of the influence of polymorphisms in key genes of the IL-6 pathway, namely IL6, IL6R, and IL6ST, may provide valuable prognostic/predictive markers for COVID-19." (PMID 37243282, 2023). "However, in COVID-19 patients, a decrease in miR-451a expression coupled with its binding to lncRNAs could amplify IL-6R/CCL2 expression at the protein level." (PMID 38140218, 2023). "Thus, the higher frequency of COVID-19 symptoms among IL6R CC genotypes could reflect the higher expression profile of this genotype and its consequent pro-inflammatory effects." (PMID 37243282, 2023). "In a situation with rapid, high, dysregulated IL-6 production, such as severe COVID-19 or a cytokine storm, repeated daily administration of an anti-IL-6/anti-IL-6R agent, or alternating daily doses of anti-IL-6 and anti-IL-6R therapies, could neutralise IL-6 activity." (PMID 35928820, 2022). "In the plasma of COVID-19 patients, the infection-related elevation of IL-6 and IL-6R results in a boost of endothelial cells and TF and this infection-induced coagulopathy may play a pivotal role in thrombocytopenia, while the cytokine storm triggers the thrombocytosis." (PMID 36295093, 2022). "Moreover, IL-6R antagonists may provide improved results for patients with infectious diseases such as COVID-19 or sepsis." (PMID 34960054, 2021). "Thus, IL-6R inhibition contributes to the development of novel treatments for COVID-19." (PMID 33404925, 2021). "Therefore, anti-IL6R treatment favors γδ T lymphocyte differentiation in COVID-19 patients." (PMID 34835019, 2021). "However, recent research discoveries revealed that both IL-6 and IL-6R blockade may reduce the benefit in patients with COVID-19." (PMID 33404925, 2021). "Tocilizumab is a monoclonal antibody targeting interleukin-6 receptor (IL-6R), inhibiting signal transduction and, thus, counteracting the effects of pro-inflammatory interleukin-6 (IL-6), that was shown to be involved in inflammatory storms in severe COVID-19." (PMID 32804279, 2021). "New data have also demonstrated that antibodies targeting IL-6/IL-6R/gp130 such as tocilizumab, siltuximab and clazakizumab could be employed for the therapy of COVID-19, as was also recommended by the National Institute of Health (NIH COVID-19 Treatment Guidelines, 2020)." (PMID 33114676, 2020).
COVID-19 (continued). "Tocilizumab, a monoclonal antibody against the IL-6R, was the first biologic agent to be largely evaluated in COVID-19 patients, also based on precipitous inclusion in the Chinese guidelines for the treatment of COVID-19 patients at the beginning of the pandemic." (PMID 33442386, 2020). "MR-link-2 also missed one (IL6R instrumented CRP levels and COVID-19) out of three true positives in the drug-target-MR analysis at lenient multiple testing thresholds." (PMID 40610416, 2025). "After the validation set (GSE171110) analysis, only four genes, namely IL-6R, TLR4, TLR2, and IFNG, showed expression changes similar to those of the training set in COVID-19." (PMID 38165854, 2024). "However, given the concordance in protection from severe COVID-19 identified in our study, randomised trial data matching that using genetic proxies for IL6R blockade, and the location of these SNPs, we can have some confidence that the effect is driven by alterations in IL6R." (PMID 36716318, 2023). "Pharmacological treatment for COVID-19 included antivirals (45.6%), azithromycin (40.5%), hydroxychloroquine or similar drugs (37.9%), anti-IL6 or anti-IL6R monoclonal antibodies (19.1%), and convalescent hyperimmune plasma (10.1%)." (PMID 36028857, 2022). "Steroids use for COVID-19, anti-IL6 or anti-IL6R treatment and admission to ICU were more common among patients who developed thrombosis in contrast to patients who did not develop thrombosis." (PMID 36028857, 2022). "While IFN-α and IFN-β were undetectable, IL-10, IL-17A and IL-18 were variably detected in COVID-19 BALF, with higher RNA and/or protein levels of IL-6, MCP-1 and IL-33 and lower IL-6 receptor (IL-6R) observed in COVID-19 BALF compared to healthy BALF19,20." (PMID 35589689, 2022). "In hospitalized patients with mild-to-moderate COVID-19, the combination of SOC with anti-IL-17A or anti-IL-6R therapy were superior or comparable to the combination with JAK1/JAK2 inhibitor, and all three were superior to SOC alone." (PMID 36001576, 2022). "Using the network pharmacology approach, we identified two clusters of genes involved in immune response (IL1A, IL2, and IL6R) and cell proliferation (CCND1, PPARG, and EGFR) mediated by biochanin A in CRC/COVID-19 condition." (PMID 34931923, 2021). "In our analysis, we identified two target gene clusters of biochanin A including inflammatory genes (IL1A, IL2, and IL6R) and cell proliferation genes (CCND1, PPARG, and EGFR) relevant to the treatment of CRC/COVID-19." (PMID 34931923, 2021). "MAS is involved in coronavirus disease-19 (COVID-19), and the blockade of pro-inflammatory cytokines by an anti-IL-6 or IL-6R antibody, such as Tocilizumab, has already been employed for the treatment of MAS and COVID-19 in patients." (PMID 35008658, 2021). "Various inhibitory antibodies directed to these targets have already been evaluated in COVID-19 patients, such as anti-IL1® (canakinumab), anti-IL6R (tocilizumab, sarilumab) or anti-TNFα (infliximab, adalimumab) antibodies." (PMID 34293006, 2021). "Our results also highlighted that the interleukin 6 receptor (IL6R) was the target of biochanin A. As a receptor of IL6, it is one of the cytokines induced in patients with COVID-19." (PMID 34931923, 2021). "Currently, corticosteroids, IL-6R antagonists, and JAK inhibitors are the only therapies showing promise for critically ill COVID-19 patients." (PMID 34485339, 2021). "To verify the relevance of these in vitro observations in COVID-19 patient samples, we measured twenty SARS-CoV-2 virus infected patient sera for detection of IL-6 and soluble IL-6R levels." (PMID 33284859, 2020). "Indeed, a number of studies identified variants located in the regulatory regions of IL6 and IL6R as genetic determinants of high IL6 circulating levels in serum and tissues that have been proposed to affect the risk and progression of many different disease states (especially COVID-19, CVD and AD)." (PMID 33339153, 2020).
COVID-19 (continued). "Tocilizumab, an anti-IL-6R antibody used in IBD treatment, is currently tested against COVID-19 in multiple clinical trials (NCT04317092 and NCT04346355)." (PMID 32714386, 2020). "Two of the most promising candidate biomarkers for both COVID-19 and neurodegenerative disorders are interleukin-6 (IL6) and its receptor (IL6R)." (PMID 33339153, 2020). "Interventions targeting COVID-19 among PICU patients included: hydroxychloroquine 63%, azithromycin 37%, corticosteroids 30%, remdesivir 27%, tocilizumab (anti-IL6R) 13%, anakinra (anti-IL1R) 13%, and intravenous immunoglobulin (IVIg) 10%." (PMID 33340348, 2020). "Humanized anti-interleukin-6 receptor (IL-6R) monoclonal antibodies are used in many inflammation-related diseases, such as active rheumatoid arthritis (RA), giant cell arteritis (GCA), cytokine release syndrome (CRS), and coronavirus disease 2019 (COVID-19)." (PMID 39767766, 2024). "In our investigation, we discerned that the levels of S1RBD IgG, along with cytokines IL-6, IL-6R, TNF-α, IL-10, and IL-1β, were markedly elevated in the individuals who received two or three doses of the mRNA COVID-19 vaccine compared to those who received a single dose." (PMID 38932387, 2024). "Lack of differences in mortality to treatment with anti-IL-6R antibodies in COVID-19 by biological sex has been described in a recent meta-analysis of RCTs22." (PMID 37598275, 2023). "Sarilumab is another type of IL-6R inhibitor studied in SARS-CoV-2, which could indicate a potential therapeutic advantage of early intervention with IL-6-modulatory COVID-19 treatments." (PMID 37124230, 2023). "A prospective observational cohort study at a national center during the first 30 pandemic months was conducted, focusing on an immunomodulatory treatment effect (dexamethasone, IL-6R/JAK-inhibition) on secondary bacterial and fungal infections among 379 critically ill COVID-19 adult patients." (PMID 37508292, 2023). "Focusing on the potential impact of pharmacological treatment for COVID-19 on the occurrence of thrombosis in the present cohort, patients who were administered corticosteroid therapy and anti-IL6 or anti-IL6R monoclonal antibody were significantly more often diagnosed with thromboembolism." (PMID 36028857, 2022). "All patients received supportive treatment per WHO recommendations, but no experimental therapeutic medications (eg, remdesivir or interleukin 6 receptor blockade with tocilizumab) for the treatment of COVID-19 were locally available." (PMID 35044430, 2022). "Nonetheless, these gene expression patterns may suggest a link between tocilizumab effects, IL6R, IL6ST, and S100A8/9 in COVID-19 patients." (PMID 35064122, 2022). "For instance, inhibition of the CCR5-CCL4 axis by Leronlima (anti-CCR5 monoclonal antibody), or the blockade of cytokine signaling by Tocilizumab (anti-IL-6R), Adalimumab (anti-TNF-α), or Anakinra (anti-IL1R) have been shown to ameliorate, in some cases, severe COVID-19 manifestations." (PMID 35269470, 2022). "The use of IL-6 or IL-6R-blocking antibodies in combination with JAK inhibitors to treat COVID-19 patients is also not recommended." (PMID 35306855, 2022). "Therefore, the sHLH that escorts serious COVID-19 with a well-defined CRS-induced ARDS urgently needs therapeutics interventions based on suppressing CRS, like glucocorticoids and some IL-6R blockers such as tocilizumab." (PMID 35250575, 2022). "Although severe COVID-19 disease increases both recruitment and exhaustion of γδ T lymphocytes in infected lung lesions but not blood, the anti-IL6R therapy with Tocilizumab promotes γδ T lymphocyte differentiation in patients with COVID-19." (PMID 34835019, 2021). "The beneficial impact of dexamethasone, acting most likely through its immune-modulating activities, on COVID-19 has been demonstrated, and early findings of the REMAP-CAP trial reported a beneficial effect of anti-IL-6R therapy in patients with COVID-19 admitted to the ICU." (PMID 34195785, 2021).